BRAF (B-Raf proto-oncogene, serine/threonine kinase)
Diseases named in the same sentence as BRAF in open-access papers (continued):
Sharing a sentence is not in itself a finding about the gene and the disease.
tumor (continued). "Caution should be taken before performing a CFI without maintenance treatment in patients with BRAF-mutated tumour or lack of tumour response at first evaluation." (PMID 32015513, 2020). "In a prospective-multicenter study, Thierry and colleagues show that cfDNA analysis could advantageously replace tumor-section analysis for KRAS and BRAF mutations." (PMID 32231042, 2020). "Our observations hint towards an aggressive tumor evolution in BRAF-MT tumors, which may already be molecularly detectable at the time of DpR." (PMID 32449003, 2020). "It is tempting to hypothesize that PIM inhibitors might prevent the adverse microenvironmental effects of BRAF inhibitors and favor the host’s immune tumor control." (PMID 32330348, 2020). "Although the healthy status mirrored by BRAFV600E is yet to be elucidated, our hypothesis is that the microbiota shift of BRAF-mutant CRC might be strongly related to the peculiar molecular profile of this tumor." (PMID 33317591, 2020). "Therefore, we combined BRAF MEKi with chloroquine and transformed a radiographically growing tumor into a long (> 18 months) and sustained stability of disease in a patient without side effects for almost 1.5 years." (PMID 31748891, 2020). "However, in tumor and normal cells expressing wild-type BRAF, these inhibitors have been found to promote BRAF dimerization, activation and binding to RAS-GTP, ultimately resulting in stimulation of MEK-ERK signaling and proliferative effects." (PMID 33042833, 2020). "The tumor cell proliferation was generally low, with only <2% Mib-1 labeling in all of the evaluated samples, irrespective of tumor stage, size, histological variant, and BRAF status." (PMID 31963551, 2020). "In BRAF-m patients, this new type of Pt-based compounds may become a barrier to tumor escape after the onset of resistance to BRAF inhibitors, possibly by extending the delay of response to BRAF inhibitors via the combination of both therapies." (PMID 33105692, 2020). "Noteworthy, in a patient with ATC resulted BRAFV600E and PD-L1 positive by NGS and IHC, sequential treatment with BRAF inhibitor vemurafenib and nivolumab led to a substantial regression of the tumor, with a complete radiographic and clinical remission 20 months after the beginning of the treatment." (PMID 33986723, 2020). "For two patients, a BRAF mutation identified in the tumour tissue was found in circulating DNA by dPCR, but was not identified by the Cobas analysis." (PMID 32664549, 2020). "While BRAF V600E mutated tumors were of lower tumor thickness and without ulceration at the time of diagnosis, most BRAF V600 positive tumor samples were recurrence/metastasis specimens (14/16) and were not from subungual sites (1/16 was subungual)." (PMID 33067454, 2020). "Another patient was found to have a BRAF mutation in the organoid culture but not in the primary tumor." (PMID 32290033, 2020). "Patients whose tumor is in the proximal colon are more likely to harbor mutations in KRAS or BRAF. t-SNE and Artificial Neural Network analyses showed systematic associations between tumor location, age, city of origin, histological subtype, and histological grade and KRAS mutational status." (PMID 32628708, 2020). "Additionally, BRAF fusions were conserved in recurrent tumor samples from three patients who progressed despite prior single-agent MEK inhibitor treatment, indicating likely preservation of this alteration following failed MEK inhibitor monotherapy." (PMID 33153497, 2020). "The increased presence of CD68+ cells and inflammatory markers in BRAF+ tumours could indicate that BRAF status may play a role in determining the response of patients to immunotherapies or immunogenic treatments." (PMID 32843682, 2020).
tumor (continued). "Clinical information for analysis included DE-mRNA signature, age, PFI status, mutational status of BRAF V600E, RAS, RET, NTRK1, and TERT, sex, histological subtype, T stage, N stage, M stage, AJCC stage, residual tumor status, extrathyroidal extension, multifocality, and anatomic site." (PMID 33553144, 2020). "However, some actionable targets can be present in other genes (notably MET, RET, NTRK, and HER2), allowing inclusion into clinical trials of patients with EGFR, ALK, ROS1, and BRAF wild-type tumors with less than 50% PD-L1-positive tumor cells." (PMID 32294880, 2020). "Patients with a mutation in BRAF, NRAS or cKIT in tumor tissue were included in this study." (PMID 33050536, 2020). "In addition to response to pharmacological modulation, BRAF status deserves further investigation as a potentially predictive biomarkers of IL-8 production in vivo, in both tumor and infiltrating mononuclear cells." (PMID 33004975, 2020). "The fourth cluster contained a mixed population of histologically diagnosed DNTs and GGs samples without BRAF mutations or cases of tumor recurrence (no other specified, NOS cluster, C4)." (PMID 31919458, 2020). "When V600E mutations exist in BRAF, BRAF is constitutively activated, causing the continued phosphorylation of MEK and ERK and thus, promoting the growth, proliferation, differentiation, migration and survival of tumor cells." (PMID 33198289, 2020). "Another common mutation that can be targeted therapeutically is the V600E mutation in the v-RAF murine sarcoma viral oncogene homolog B1 (BRAF), which constitutively activates the BRAF kinase, resulting in sustained extracellular signal-related kinase (ERK) signaling and increased tumor growth." (PMID 33299639, 2020). "Moreover, miR-579 3p has been found to be downregulated in tumor samples derived from patients before and after the development of resistance to target-based therapies as well as in cell lines resistant to BRAF/MEKi." (PMID 32013263, 2020). "In addition, tumor signaling pathways that are regulated by BRAF, HIF-1α, c-MYC, and mTOR are accelerated to activate glycolysis in the cancer cells and accumulation of lactate in the microenvironment of the tumor." (PMID 32213878, 2020). "Currently, it is not known whether this mechanism is also involved in p21CIP1 regulation upon mortalin depletion in BRAF tumor cells." (PMID 32751750, 2020). "Mutations in certain genes may alter tumor biology to more aggressive phenotypes, such as KRAS or BRAF mutation in colorectal cancer." (PMID 32024876, 2020). "It is noteworthy that concordance between tumor and plasma samples was 100% for all mutations with the exception of BRAF, where 4 additional plasma samples had detectable mutations not seen in their matched tumor samples." (PMID 32284750, 2020). "Finally, a combination therapy using BET inhibitors along with a BRAF or an ERK inhibitor prevented tumor cell resistance and growth." (PMID 32907612, 2020). "We evaluated clinical data and performed genetic testing on 46 spinal LGG (WHO grade 1 or 2) with available tumor samples and mapped PFS and OS of these patients to see if an association between aberrations in BRAF, treatment, and OS could be identified." (PMID 33063010, 2020). "By RNA-seq analysis, we identify a RET rearrangement in the tumour material of a patient who does not harbour any known RAS or BRAF mutations." (PMID 32345963, 2020).
tumor (continued). "The 729 diagnostic tumor samples that were evaluated with the smMIP panel showed 788 (likely) pathogenic mutations, including mutations that give access to targeted treatment options (e.g. mutations in EGFR, BRAF, MET, ERBB2, KIT, PDGFRA)." (PMID 32264863, 2020). "BRAF status had significant effects on gene expression within the tumour." (PMID 32843682, 2020). "The potency of these MMAF-based ADCs was confirmed on melanoma cells that overexpress the receptor tyrosine-protein kinase erbB-3, which is also known as HER3 (HER3 allows the escape of tumor cells from vemurafenib-targeted treatment of BRAF-positive melanoma cells)." (PMID 32899183, 2020). "BRAF-mCRC would be recognized as a tumor which had these characteristics." (PMID 33152998, 2020). "Within our cohort of T4 tumors, those carrying BRAF V600E mutation revealed no significant univariable correlation with patient age, gender, tumor size, regional lymph node or distant metastasis." (PMID 32415114, 2020). "There is evidence from in vitro and in vivo studies that the enhanced tumour infiltration by T cells might be due to a reduction in vascular endothelial growth factor (VEGF) expression during BRAF inhibitor administration." (PMID 32645969, 2020). "Using 1010 matched case-control pairs within the NSHDS, we investigated circulating levels of insulin, C-peptide, adiponectin, and leptin in relation to the risk of CRC, and molecular subtypes of CRC defined by KRAS and BRAF mutation status and MSI status in the tumor." (PMID 32210264, 2020). "Furthermore, these miRNAs decrease drug sensitivity to BRAF inhibitors, promoting tumour cell proliferation, survival and invasion." (PMID 33203119, 2020). "The presence of BRAF V600E is associated with an increased risk of tumor relapse and a lack of response to iodine therapy." (PMID 32575591, 2020). "Genomic analysis found that her tumor did not contain any common RET mutations but did harbor a BRAF V600E mutation." (PMID 32231814, 2020). "FDA-approved RAF inhibitors poorly inhibit BRAF dimers, which leads to tumor resistance." (PMID 32873792, 2020). "However, the immune response to BRAF-targeted therapies occurs early, but this response is lost upon tumor progression." (PMID 32260561, 2020). "Lifirafenib is an investigational, reversible BRAF V600E inhibitor as well as an inhibitor of A-RAF, B-RAF, C-RAF, and EGFR that was studied in a phase I, dose-escalation trial investigating the safety and efficacy of the drug in BRAF mutant as well as RAS mutant sold tumor patients." (PMID 33182254, 2020). "First, we studied the relationship between the distance of the center of the tumor from the thyroid surface and the clinicopathologic variables (including tumor subtype and BRAF V600E status), the characteristics of tumor growth, and the microscopic appearance of the tumor." (PMID 31963890, 2020). "Notably, the authors also observed that BRAF exon 15 p.V600E mutant CRC patients featuring microsatellite-stable (MSS) tumor patterns had significantly lower OS rates than MSI tumors, regardless of the stage of the disease (II to IV)." (PMID 33260892, 2020). "In this review, we will examine the double facets of BRAF gene alterations in different tumor types to highlight the clinical relevance of this biomarker not only in improving the pathological assessment of human solid neoplasms but also in facilitating treatment decision-making and outcomes." (PMID 33260892, 2020). "Compared to patients in the L-immunity group, patients in the H-immunity group showed a more advanced stage, larger tumor size, more lymph node metastasis, higher tall-cell PTC proportions, lower follicular PTC proportions, more BRAF mutations and fewer RAS mutations." (PMID 33193087, 2020). "Moreover, combinatorial photothermal effects and BRAF knockdown by GAL-GNR-siBRAF effectively given rise to tumor cell death." (PMID 32449085, 2020).
tumor (continued). "For example, separate testing for the BRAF c.1799T>A variant (p.V600E), following FLA or IHC, is recommended to increase the specificity of LS screening, but both MSI and BRAF can be analyzed by a single tumor sequencing assay." (PMID 31471937, 2020). "Given broad and pleiotropic Gal‐1 functions, the expression of this protein might be a likely explanation to several additional effects observed in the tumor microenvironment following BRAF inhibition." (PMID 32330348, 2020). "Since oncogenic driver alterations may modulate immune response in tumor microenvironment that may influence prognosis in LUAD, the effects of EGFR, ALK, ROS1, and BRAF alterations on tumor microenvironment remain unclear." (PMID 33585210, 2020). "In our study, no trend or possible association between BRAF mutation and tumor thickness was observed." (PMID 32775409, 2020). "BRAF V600E mutations were linked to GG with CD34 expression, FGFR1 mutations to DNT, MYB alterations to AG and also IDG and PRKCA fusions to PGNT, suggesting the possibility to also develop a genetically driven tumor classification scheme for LEAT." (PMID 32151273, 2020). "In our study, V600E BRAF mutations were absent in pretreated tumor biopsies; this confirmed the data from other studies." (PMID 31998419, 2020). "An additional 65 studies contained relevant data for KRAS, NRAS, or BRAF mutation status and tumor sidedness but did not report data specific to the mCRC population or data for mutation status by tumor sidedness." (PMID 31856410, 2020). "In regard to these and our results, it seems reasonable to recommend a maintenance chemotherapy rather than CFI in patients with BRAF-mutated tumour." (PMID 32015513, 2020). "Though with different severity, all three engineered systems displayed a similar tumor phenotype supporting the hypothesis of an in vivo partial ceRNA regulation of BRAF through BRAF-rs1." (PMID 32605220, 2020). "On the other hand, a combination of DNMTi that reinstate RASSF1A expression in combination with RAF inhibitors may lead to the activation of apoptosis in BRAF mutant tumours." (PMID 31963420, 2020). "In particular, our observations hint towards an aggressive tumor evolution in patients with BRAF-MT tumors, which may be molecularly detectable at the time of DpR." (PMID 32449003, 2020). "On the other hand, the sample identified by NGS but not by RT-PCR, a BRAF mutation in codon V600K, measured 100 mm2 with a tumor representation of 80% and a DNA concentration of 87.1 ng/μl." (PMID 36046072, 2020). "The correlation of these four mPTC groups with clinicopathologic features, including tumor subtype and BRAF V600E status, the characteristics of tumor growth, and the microscopic appearance of the tumor, was analyzed to investigate their possible relevance for risk stratification." (PMID 31963890, 2020). "We speculate that somatic mutations in genes such as BRAF and RAS in PTC may initiate the changes in the tumor immune microenvironment." (PMID 33193087, 2020). "If the hypermethylation and no BRAF mutation occur in the tumor tissue, it is recommended to analyze MLH1 promoter methylation results in the healthy tissue to determine epimutation." (PMID 33027913, 2020). "However, at multivariate analysis for OS, including age and ECOG PS, only tumor grade and BRAF status resulted independent prognostic factors for survival." (PMID 32872561, 2020). "Altogether, it is assumed that BRAF mutation-mediated ERK phosphorylation can change the activity of these transcription factor-mediated gene expressions dynamically in cancer cells and exhibit tumor phenotypes." (PMID 33198372, 2020). "In an attempt to improve the understanding of immune activity in molecular subgroups of CRC, we analysed the distribution of different immune cell subsets in relation to tumour MSI/MSS status, CMS subtype, as well as BRAF and KRAS mutation status, and identified several significant relations." (PMID 33228141, 2020).
tumor (continued). "BRAF and KRAS mutations could lead to the abnormal activation of Ras-Raf-MEK-ERK pathway, thus promoting the growth and proliferation of tumor cells." (PMID 33088218, 2020). "Their most recent multicenter study that included 743 PTMC patients, treated with total thyroidectomy, showed a significantly higher risk of tumor recurrence in BRAF positive group than BRAF negative one, 10.8% vs. 6.4%, respectively." (PMID 33123090, 2020). "All patients with positive KRAS or BRAF-mutated ctDNA presented the same mutation in their tumor with no false positive cases." (PMID 32517177, 2020). "When MSI-H and lack of expression of both MLH1 and PMS2 are observed, tumor BRAF V600E mutation and/or MLH1 promoter hypermethylation testing is recommended to distinguish sporadic colorectal cancer from CRC caused by an MMR defective system." (PMID 33027913, 2020). "Targeted DNA sequencing identified a BRAF V600E mutation in the tumor, without recurrent mutations in IDH1, IDH2, TERT promoter, FGFR1, H3F3A, or HIST3H1B." (PMID 32811569, 2020). "If there is no BRAF mutation in a tumor, performing further genetic tests for MLH1 and PMS2 germline mutations is recommended." (PMID 33027913, 2020). "In contrast, the tumor cells tested negative for p63, p40, smooth muscle actin, S-100, cytokeratin 5/6, thyroglobulin, BRAF V600E, and Epstein-Barr virus-encoded small RNAs." (PMID 32438756, 2020). "In tumors with mutations of KRAS, NRAS, PIK3CA, or BRAF, the proportion of VAF with different mutations in tumor cell samples of the same patient varies significantly, which may also reflect the ITH of tumor cells." (PMID 32853464, 2020). "For tumours with RAS or BRAF mutations with already maximal intrinsic ERK signalling, ERK mediated immune cell activation may shift the balance towards tumour suppression." (PMID 32753665, 2020). "Tumor 2 is an “M” class tumor (tumor driven by mutation rather than CNAs) typified by a high confidence BRAF:p.G469A:c.1406G>C somatic mutation with less genomic instability compared to the TADE and NE." (PMID 32426287, 2020). "We hypothesized that if resistance to JQ1 provided by FBXW7 S462P occurs through BRAF signaling then specific inhibition of BRAF or the downstream ERK/MEK pathway should impede tumor growth advantage." (PMID 32907612, 2020). "Although the detected KIT mutations are different from activating mutations found in other KIT-dependent neoplasms, our data suggest that KIT-inhibitors might have a role in treating BRAF-wt LCH patients." (PMID 32372223, 2020). "Nevertheless, BRAF mutation was detected in 4 cfDNA samples but not in their matched tumor samples, to exclude false positive possibility in the analysis of cfDNA samples, it is better to perform DNA sequencing on these 4 samples for BRAF mutation." (PMID 32284750, 2020). "Likewise, Bcl-2, PTEN, KRAS, and BRAF are the genes that regulate apoptosis, acting as an important signaling molecule of their downstream pathway involved in the formation of tumor resistance." (PMID 32695666, 2020). "Analysis of BRAF mutation status showed no mutation for codons 600, 464, 466, and 469 in both parental tumor tissue and cell populations." (PMID 32927768, 2020). "However, the induction of BH3-only proteins by BRAF inhibition efficiently primes tumor cells for apoptosis, allowing them to straightforwardly tilt the balance toward cell death by co-targeting the pro-survival Bcl-2 family members." (PMID 33396645, 2020). "Inhibition of BRAF led to a significant increase in the HP pyruvate‐to‐lactate label exchange as soon as 24 hours after treatment administration, before any significant tumour shrinkage." (PMID 31833658, 2020). "However, once resistance to BRAF inhibitors develops, the tumor microenvironment reverts to its low immunogenic state, with fewer infiltrating T-cells and NK cells, more double-negative T-cells, and restoration of myeloid-derived suppressor cells." (PMID 33003483, 2020).